SPARC (secreted protein acidic and cysteine rich)
Diseases named in the same sentence as SPARC in open-access papers (continued):
Sharing a sentence is not in itself a finding about the gene and the disease.
tumor (continued). "Furthermore, the tumor suppressor KLF4 decreases tumor invasion by downregulating the expression of SPARC." (PMID 35981080, 2022). "In the oral cavity, increased SPARC immunoreactivity on the tumour stroma and the tumour cells in OSCCs has been positively correlated with the presence of distant metastases and patient survival, indicating that SPARC could have a prognostic role of in OSCC." (PMID 34205668, 2021). "The studies have shown that SPARC overexpression could act as a tumor suppressor gene, which inhibits cancer proliferation, invasion, and angiogenesis in certain types of cancer, including gastric cancer, medulloblastoma, ovarian cancer, and prostate cancer." (PMID 34912848, 2021). "Tumor cell PDGFRB and stromal SPARC expression in particular were associated with shorter survival and may play critical roles in the pathogenesis of MPM." (PMID 33955203, 2021). "Recent studies report SPARC expression by neoplastic cells in epithelioid osteosarcoma of the mandible and the ECM of mucoepidermoid carcinoma of salivary glands where its expression is associated with low histological grade tumour." (PMID 34205668, 2021). "High tumor cell PDGFRB and high stromal SPARC were independently associated with survival." (PMID 33955203, 2021). "A multivariable survival analysis adjusted for clinical parameters and stromal mfIHC markers revealed that tumor cell PDGFRB and stromal SPARC remained independently associated with survival (HR = 1.01, 95% confidence interval [CI] = 1.00–1.03 and HR = 1.05, 95% CI = 1.00–1.11, respectively)." (PMID 33955203, 2021). "Interestingly, the serum SPARC level has been proposed as a pancreatic cancer marker, as it has also been correlated to tumour size." (PMID 34827687, 2021). "Interestingly, SPARC mRNA expression was observed to be significantly elevated in the tumor stroma as compared to the normal breast in several patient cohorts." (PMID 33534863, 2021). "In addition to the cell experiments in vitro, we further investigated the effect of SPARC overexpression on tumor growth in vivo." (PMID 34912848, 2021). "Similarly, cath-D secreted by TNBC cells cleaved fibroblast- and cancer cell-derived SPARC at the tumor pericellular acidic pH." (PMID 33995652, 2021). "Therefore, we must consider TSP1/SPARC’s multiple effects along with the type of tumor and stage of the disease if we want to consider it as a future preventive treatment for cancer recurrence." (PMID 33987095, 2021). "Thus, in addition to analyzing the SPARC expression in tumor tissues, we also analyzed the difference of SPARC mRNA expression levels in PBMC from LIHC patients and normal controls based on GSE58208 and GSE49515 datasets." (PMID 34912848, 2021). "Since we also found increased mRNA levels of these myokines in human myotubes after exercise-mimicking EPS, it is possible that IL6, irisin and/or SPARC also contribute to the anti-tumour effects of our exercise-conditioned patient serum and muscle cell medium." (PMID 34359731, 2021). "FL SPARC stimulates migration and invasion of TNBC cells 63, and promotes MMP-2 activation in TNBC cells, thereby contributing to the proteolytic cascades associated with tumor invasion." (PMID 33995652, 2021). "Further studies to compare the effects of SPARC in the tumor and the stroma are warranted." (PMID 33534863, 2021). "More drugs enter tumor cells through active targeting mediated by gp60-cellar protein-SPARC." (PMID 34109887, 2021). "The correlation between the SPARC genetic variants and efficiency of tumor angiogenesis was not addressed in these studies." (PMID 34209679, 2021). "Furthermore, cancer cells often overexpress albumin binding glycoprotein SPARC (an acid-secreting protein rich in cysteine), which promotes the release of drugs in tumor regions for a better targeted antitumor effect." (PMID 35047380, 2021).
tumor (continued). "According to a study, both mir-148b and mir-152 can reactivate some tumor suppressor genes such as SPARC and BNIP3 by targeting DNMT-1, thereby resulting in modification of methylation status of the mentioned tumor suppressor genes and reducing tumorigenic properties in pancreatic cancer cell lines." (PMID 33632341, 2021). "These opposing actions of SPARC may be due to the peculiar molecular mechanisms characterizing the various tumor types, as well as by the differential expression of cancer-specific proteases." (PMID 34199373, 2021). "Other factors including interactions with tumor microenvironment including extracellular matrix, stromal cells or proteolysis of SPARC may be involved but the mechanism remains largely unknown." (PMID 33579227, 2021). "As the tumor extracellular environment is acidic 44, we then asked whether cath-D can degrade SPARC in the TNBC extracellular medium at low pH." (PMID 33995652, 2021). "Indeed the more SPARC present in a tumor the more the tumor is prone to metastasis highlighting the clinical role of this molecule." (PMID 33633185, 2021). "An inverse correlation between the epigenetic silencing and SPARC expression was confirmed by 5-Aza-2′-deoxycytidine ((5-Aza-CdR) treatment that also significantly induced a reduction in cell viability, proliferation and tumor cell migration." (PMID 32580473, 2020). "This investigation should also be performed by considering that many other epigenetic factors that enhance DNA methylation status could ultimately affect SPARC expression in the tumor." (PMID 32580473, 2020). "The CCK-8 assay, colony formation assay and tumour xenograft experiment demonstrated that SPARC could reduce the tumour-promoting effects of M2." (PMID 32226513, 2020). "Recently, emerging evidence has shown that SPARC could also affect the malignant process in various solid tumours, and its function is highly heterogeneous among tumour types 13-15." (PMID 32226513, 2020). "It is hypothesized that the different expressions and functions of SPARC might be attributed to the specified tumor type and surrounding environment of the tumor cells." (PMID 31897236, 2020). "SPARC is negatively correlated with tumour TNM stage and local lymph node metastasis." (PMID 32226513, 2020). "SPARC is known to facilitate albumin accumulation in tumor stroma." (PMID 33114661, 2020). "Knockdown of SPARC significantly decreased tumor weight in mice." (PMID 32670867, 2020). "It has been hypothesized that the accumulation of albumin in the tumor interstitium is facilitated by SPARC." (PMID 31858848, 2020). "We generated a shRNA lentiviral vector specifically directed against the SPARC transcript to determine whether the EN2-mediated tumor proliferation, migration and invasion are dependent on SPARC expression." (PMID 32117645, 2020). "Although previous studies have focused on the effects of tumor-derived SPARC on biological behaviours such as tumour proliferation and migration, the behaviours of SPARC from macrophages remains poorly understood, because the roles of SPARC from different cell origins are highly heterogeneous." (PMID 32226513, 2020). "Interestingly, among NSCLC patients with early tumor stage (I–II), the estimated overall survival was dramatically reduced from 80% to 10% when SPARC methylation levels passed from 0 to 300 and thereafter tended toward 0% for greater values." (PMID 32580473, 2020). "When BGC-823 and SGC-7901 cells were cultured in SPARC overexpressing M2 conditioned medium, the number of tumour cells that could pass through the upper chamber was significantly reduced compared with that of the control group." (PMID 32226513, 2020). "Apart from confirming targets, such as ERBB2 and S100A11, which are exclusively upregulated in the tumour epithelial cells, qPCR data confirmed that stromal targets such as SPARC, TIMP1, IGFBP7, COL1A1 were upregulated specifically in stromal components and not in epithelial components." (PMID 31959771, 2020).
tumor (continued). "Therefore, we used an anti-SPARC antibody to label tumor vessels (green) to examine the localization of SPARC relative to that of Pt NPs labeled with ICG (indocyanine green; near infrared fluorescence probe)." (PMID 31992692, 2020). "In 3 out of 4 tumor cell lines high SPARC methylation levels were observed." (PMID 32580473, 2020). "SPARC is an extracellular glycoprotein that affects tumor cell proliferation, apoptosis, angiogenesis and invasion and has been reported to be overexpressed in a broad range of human malignancies, including ESCC, upon obtainment of invasive or metastatic behaviors 5-14." (PMID 31897236, 2020). "In addition, it has been reported that albumin-binding receptors (e.g., SPARC and gp60) are overexpressed on tumor cells and tumor vessel endothelium to increase the uptake of nutrients necessary for growth." (PMID 32659914, 2020). "When expressed within the tumor, SPARC could be protective and possibly buffer the aggressiveness of the tumor itself, highlighting the tissue-specific functions of SPARC in assisting crosstalk at the tumor-stroma interface." (PMID 32580473, 2020). "However, a still open question is if SPARC is produced by platelets and released on the tumor site, or it is taken up by platelets from tumor cells." (PMID 33383671, 2020). "Besides, SPARC has also been documented to be involved in multiple malignant tumor behaviors, including cell proliferation, apoptosis and invasion 6-7." (PMID 31897236, 2020). "A statistically significant effect was found for tumor stage, chemotherapy, and SPARC expression." (PMID 31554208, 2019). "Confocal microscopy analysis revealed that SPARC-deficient MDSC showed a significantly lower amount of p50 but not of p65 into the nucleus than SPARC-competent MDSC, at baseline or when in culture with SN25ASP tumor supernatant." (PMID 31281314, 2019). "We investigated whether SPARC can influence tumor angiogenesis as part of their pro-tumorigenic activities." (PMID 31281314, 2019). "Additionally, the SPARC promoter can drive the expression of a suicidal gene that can suppress tumour cell growth." (PMID 31139014, 2019). "U87MG tumors showed higher expression of SPARC in tumor tissues than U87MG-shSPARC tumors." (PMID 31695779, 2019). "Therefore, in the tumor intestitium, SPARC binds to albumin-bound PTX, which facilitates release of PTX near cancer cells and increases the antitumor efficacy of nab-PTX." (PMID 31783552, 2019). "Because SPARC is secreted form of protein, it can affect to tumor microenvironment." (PMID 31695779, 2019). "Interestingly, while SPARC was found to be highly upregulated in the “activated” stroma subtype associated with poor prognosis, α-SMA was described as a marker for tumor-restraining myofibroblastic CAFs (myCAFs)." (PMID 31878349, 2019). "In a 3D co-culture system, fibroblast-derived SPARC enhanced tumor cell invasion." (PMID 31554208, 2019). "Conceivably, the effect of SPARC on tumor dormancy may be due to the elevated level of periFN assembly, which is worth further researching." (PMID 31861892, 2019). "Therefore, we determined the effect of host-SPARC on the metabolic adaptation of ID8 omental tumour nodules developing in SP–/– and SP+/+ mice." (PMID 30765860, 2019). "Our findings in the present study indicate that SPARC exerts a tumour-suppressor effect on OvCa cells in part through inhibiting their interactions with omental adipocytes; the main site of metastasis of OvCa, and the most common cause of mortality in OvCa patients." (PMID 30765860, 2019). "Recently, a mannosylated albumin delivery platform able to target both SPARC and CD206 was proposed in order to provide a more efficient way to target drug-resistant cancer cells and reprogram tumor-associated macrophages that over-express the mannose receptor." (PMID 31195727, 2019). "Most importantly, we observed SPARC-mediated HSA accumulation in tumor tissues." (PMID 31695779, 2019).
tumor (continued). "Furthermore, secreted protein acidic and rich in cysteine (SPARC) synthesized by TAMs were shown to be necessary for the migration of tumor cells, aside from its role as an ECM deposition regulator." (PMID 31300030, 2019). "In addition, SPARC, an extracellular protein involved in the deposition and modelling of the extracellular matrix that is downregulated in many tumour types was found to be up-regulated (3.6 folds) by PRP treatment." (PMID 31388092, 2019). "Knocking down SPARC expression significantly waken tumor dormancy and drastically lowered bone metastasis-free survival of tumor-bearing mice, suggesting SPARC plays a central role in maintaining tumor dormancy." (PMID 31861892, 2019). "To evaluate whether human myeloid cells express SPARC in situ in the tumor microenvironment (TME) we performed a double staining confocal microscopy analysis of BC paraffin sections." (PMID 31281314, 2019). "The role of SPARC in carcinogenesis is complex and variable for different tumor sites." (PMID 29623263, 2018). "While the prevalence of Ca2+ binding domains in this protein hint at a role in SPARC function, the exact pathway through which a Ca2+-SPARC complex elicits tumor advancement remains largely unknown." (PMID 29636894, 2018). "This demonstrated that SPARC plays a key role in the tumor-targeted delivery of the albumin NPs." (PMID 29732051, 2018). "Western blot analysis of KPC tumours (n=5) and matched liver metastases (n=5) further corroborated these findings showing low expression of important stromal components such as fibronectin, SPARC and α-SMA in metastases." (PMID 28077438, 2018). "In the present study, we report a novel role of SPARC as a tumor suppressor in OvCa." (PMID 30332737, 2018). "SPARC, a multifunctional, matricellular Ca2+ binding protein, overexpressed in glioblastoma and thyroid, esophageal, hepatocellular, and pancreatic carcinomas, has been clinically correlated with tumor progression." (PMID 29636894, 2018). "In the specific tumor microenvironment, SPARC may facilitate the degradation of the basement membrane barrier and contribute to the conversion from in situ to infiltrating cancer." (PMID 30544617, 2018). "Moreover, tumor-derived SPARC is known to promote metastatic colonization through increasing vascular permeability." (PMID 30323895, 2018). "Hypomethylating agents such as azacitidine can upregulate SPARC in tumors, which may enhance the accumulation of albumin-bound drugs at tumor site." (PMID 28881739, 2017). "In addition, grade IV tumor samples express relatively high SPARC levels in comparison of grade I to III tumor samples." (PMID 28718842, 2017). "Reduced exposure of tumor cells to SPARC facilitates tumor growth process." (PMID 29156791, 2017). "SPARC expression was observed not only in tumor cells, but also in stromal cells." (PMID 28050738, 2017). "The mechanism in this case may be the overexpression of SPARC with resultant accumulation of nab-paclitaxel at tumor site." (PMID 28881739, 2017). "In some tumor types, SPARC has been shown to act as a tumor suppressor." (PMID 28881739, 2017). "Additionally, SPARC affects tumour cell behaviour to activate the PI3K (phosphoinositide-3-kinase)-AKT pathway, a key mediator of cell survival." (PMID 29176935, 2017). "The present study focused on the role of SPARC in tumor cells." (PMID 28718842, 2017). "However, once primary tumor invaded into the adjacent organs through the serosa, the positivity of SPARC was significantly decreased, instead." (PMID 29156791, 2017). "To characterize whether anti-tumor macrophages are compromised under tumoral conditions, we analyzed SPARC and TyrRS expression." (PMID 29162623, 2017). "SPARC expressed by CAF might act as a tumor inhibitor during the early stage since SPARC protein can induce apoptosis in tumor cells." (PMID 29156791, 2017).
tumor (continued). "This is the case with albumin-coated paclitaxel (nab-PTX) and the interaction with SPARC (secreted protein acidic and rich in cysteine), overexpressed in increased tumor invasion and metastasis: SPARC-positive patients responded better (83%) to nab-PTX than SPARC-negative patients." (PMID 29023366, 2017). "Among the cDNA array assays, the highest SPARC expression is detected in grade IV tumor samples." (PMID 28718842, 2017). "The upregulated proteolytic enzyme FAP and SPARC are also signs of a tumor-specific matrix." (PMID 29176937, 2017). "SPARC was found in various tumors and was expressed by either tumor cells or tumor stromal cells." (PMID 29156791, 2017). "And SPARC plays an important role in the occur of cancer and tumor progression." (PMID 29262657, 2017). "As mentioned in Section 2.5, SPARC exhibited a tumor suppressor effect." (PMID 29065446, 2017). "The choice of using azacytidine priming was to increase SPARC levels within the tumor, which may enhance accumulation of albumin-bound drugs at the tumor site." (PMID 28881739, 2017). "Moreover, monocytes can differentiate into macrophages which can contribute to tumor metastasis by producing SPARC/osteonectin." (PMID 29108302, 2017). "SPARC is secreted from cancer cells and neighboring stroma (tumor microenvironment)." (PMID 28969021, 2017). "In different types of human cancers, SPARC plays either an oncogenic or tumor-suppressive role." (PMID 28969021, 2017). "Further investigation including functional and mechanistic studies must be undertaken in order to address the biological implications of these miRNAs and to elucidate their involvement in SPARC mediated effects on tumor suppression, treatment response and resistance." (PMID 28435518, 2017). "SPARC expression is frequently detected in tumor-associated stroma, but is not in pancreatic ductal adenocarcinoma." (PMID 28718842, 2017). "SPARC has been hypothesized to enhance tumour uptake of an albumin-based nanoparticle system of nab-paclitaxel (Abraxane®) though direct evidence remains to be elucidated." (PMID 26925240, 2016). "One caveat to consider is that since SPARC may alter both the tumor microenvironment and treatment response, therapies targeted to modulate SPARC function may affect both delivery and response to chemotherapy." (PMID 27622658, 2016). "Using stabilin-1 knockout mice we demonstrated that the absence of stabilin-1 on TAM results in reduced growth of TS/A mammary adenocarcinoma which is accompanied by impaired endocytic clearance function of TAM and reduced uptake of SPARC capable of inducing TS/A tumor cell death." (PMID 27105498, 2016). "Since SPARC is secreted into the extracellular tumor microenvironment and is required for TGFBI fibrillar deposition, its expression may indirectly influence chemotherapeutic response." (PMID 27622658, 2016). "A necessary initial goal in the present study was to demonstrate that spheroids (urospheres) could be isolated from the non-SPARC transfected As+3-and Cd+2-transformed cell lines and that urospheres could initiate a tumor in immune-compromised mice." (PMID 26783756, 2016). "All studies investigated SPARC in cancer cells or stromal cells of tumor tissues by IHC or RT-PCR." (PMID 26731428, 2016). "The low level of expression of the SPARC protein in lysates from the tumor transplants represents the average expression of SPARC within the entire tumor population, leaving the possibility of some focal expression of SPARC within the malignant urothelial component of the tumor." (PMID 26783756, 2016). "Immunostaining for the SPARC protein, which is a technique capable of identifying SPARC protein expression in small, focal areas of a tumor, was performed on formalin fixed, paraffin embedded samples of the tumor transplants generated from the SPARC transfected As+3 and Cd+2 cell lines." (PMID 26783756, 2016).